STAT1 (signal transducer and activator of transcription 1)
Diseases named in the same sentence as STAT1 in open-access papers (continued):
Sharing a sentence is not in itself a finding about the gene and the disease.
colitis (continued). "In renin transgenic mice, tofacitinib inhibited the phosphorylation of JAK2 and STAT1/3 leading to the attenuation of colitis and better survival." (PMID 37877017, 2023). "PCSK6 binds to STAT1 to promote STAT1 phosphorylation and regulate Th1 cell differentiation, thus promoting the M1 polarization of macrophages and aggravating colitis progression." (PMID 37211384, 2023). "Despite being evolutionarily low conserved, NTE is necessary for the recently discovered dephosphorylation of PHLPP1 transcriptional regulatory substrate signal transducer and activator of transcription 1 (STAT1) in colitis." (PMID 37576883, 2023). "In conventionally housed IL-37tg mice with DSS induction, IL-37 receptors Il-18r1 and Il1rapl1 mRNA levels and additional downstream signaling pathway genes (Jun, Myd88, Sigirr, Smad3, Stat1, and Stat3) were expressed similarly as in control WT colitis mice." (PMID 35836813, 2022). "The anti-inflammatory effects of koreanaside A on LPS-induced macrophages and DSS-induced colitis are related to inflammatory regulation of the AP-1, NF-κB and STAT1/3 signalling pathways." (PMID 35326124, 2022). "Moreover, we identified that STAT1 signaling might be associated with tissue injury processes in the colon as Casp8ΔIECx Stat1−/− mice exhibited severe tissue injury and inflammation in response to experimental colitis." (PMID 34141714, 2021). "Small molecule compounds inhibiting STAT1 signaling have been shown to improve disease in experimental colitis by selective sequestering of STAT1 from the receptor." (PMID 34068714, 2021). "In the TNBS mouse model of colitis, berberine reduces IFNγ, IL-1α, IL-6, IL-17, and TNFα expression in colonic tissues and sera and suppresses Th1 and Th17 cells through reduction of STAT1, STAT3, and NF-κB phosphorylation." (PMID 32855621, 2020). "To investigate the role of STAT1 signaling in T-cell driven colitis, we adoptively transferred unfractionated WT or Stat1−/− CD4+ T cells into Il10rb−/−Rag1−/− mice." (PMID 30796216, 2019). "Here we describe a role for STAT1 in enabling T cells to induce colitis by protecting them from NK cell-mediated cytotoxicity." (PMID 30796216, 2019). "We employed mice with specific deletion of STAT1 in intestinal epithelial cells (STAT1∆IEC) to investigate sex‐specific functions in colitis and colitis‐associated CRC." (PMID 29419930, 2018). "We performed short‐term treatment of mice with DSS to investigate sex‐specific STAT1 functions in acute colitis." (PMID 29419930, 2018). "The involvement of IFN-γ in tissue remodeling and disease progression is further emphasized by observations in double Tcra−/−Socs1−/− mice where colitis is characterized by excessive IFN-γ-mediated STAT1 signaling." (PMID 24412616, 2014). "The anti-colitis efficacy of a T. versicolor extract has also been demonstrated in an experimental colitis mice model, in which the oral administration of the extract suppressed the gene expression of STAT1, STAT6, IL-4, and IFN-γ." (PMID 24019869, 2013). "Furthermore, the increased pathological severity of colitis and CD45+ leukocyte infiltration in DSS-treated Rbbp9-/- mice was completely abolished by the simultaneous loss of STAT1 in Rbbp9-/-;Stat1-/- mice." (PMID 39631567, 2025). "Among the members of the STAT family, the expression and activation of STAT1 are predominantly upregulated in UC and may, therefore, play a critical role in the pathophysiology of colonic inflammation." (PMID 39631567, 2025). "In TNBS-induced colitis, Berberine increases the expression of sIgA in the colon by downregulating STAT1 and STAT3 phosphorylation, inhibiting the NF-κB signaling pathway, decreasing Th1/Th17, and reducing pro-inflammatory cytokines, which can regulate the immune response homeostasis." (PMID 35873579, 2022).
colitis (continued). "It has also been reported that ginseng polysaccharides could improve the DSS-induced colitis by inhibiting the JAK2/STAT1/NLPR3 inflammasome-signaling pathway in mice, as well as enhance ginsenoside Rb1 absorption and affect gut microbial metabolism." (PMID 35327312, 2022). "In addition to the hematopoietic defects documented above, STAT1 KO mice developed spontaneous colitis, frequently accompanied by rectal prolapse." (PMID 34378531, 2021). "We therefore suggest that GC-C via cGMP modulates STAT1 content and activity in the intestinal epithelium, leading to a basal inflammatory signal observed in S839I mice that is exacerbated in the presence of a colitis-inducing agent." (PMID 34546338, 2021). "In addition, probiotic treatment or FMT can reduce the expression and secretion of inflammatory factors (such as IFN-γ, IL-12, TNF-α, IL-6, and IL-1β) to resist colitis by regulating STAT1, STAT4, or NF-κB signals." (PMID 33532501, 2021). "In addition, we tested the sensitivity of STAT1 KO mice to dextran sulfate sodium (DSS)-induced colitis." (PMID 34378531, 2021). "According to the present findings and our previous study, we hypothesize that SARI impairs CAC through attenuating colitis by directly targeting and promoting protease‐dependent degradation of STAT1 and the transcriptional activity of STAT1/MCP‐1." (PMID 31578820, 2020). "While it was noted that Stat1−/− T cells were unable to cause colitis, the profile of Stat1−/− T cells in vivo was not analyzed and STAT1 was assumed to act in a similar fashion as T-bet13." (PMID 30796216, 2019). "This differentiation profile was however seen in both control and NK cell-depleted Il10rb−/−Rag1−/− mice, suggesting that the primary role of STAT1 in T-cell-driven colitis is to protect the T cells from NK mediated elimination, rather than to repress their intrinsic Th17 differentiation potential." (PMID 30796216, 2019). "However, a recent study has suggested that epithelial STAT1 protects from DSS‐induced colitis in mice." (PMID 29419930, 2018). "Additionally, a decrease in Th1-type cytokine production and a reduction in chemically-induced colitis was observed in mice when pharmacological inhibition of STAT1 was performed." (PMID 30235866, 2018). "DSS‐induced colitis is the tumor‐promoting condition in the azoxymethane/dextran sulfate sodium (AOM‐DSS) model of colitis‐associated CRC, and we wondered if sex‐specific STAT1 effects in colitis and CD8+ T‐cell infiltration impact tumor formation." (PMID 29419930, 2018). "To investigate whether inhibition of colitis in gp130757F/F miceis due to altered gp130 signalling, we examined activation of signallingmolecules STAT1, STAT3, ERK1/2 and NfκB in the colon of DSS-treatedand untreated gp130757F/F and WT mice." (PMID 26848037, 2016). "As expected, STAT1 levels were significantly reduced in IFN-γ−/− mice, suggesting that caspase-11 regulation during colitis may occur via a type II IFN-STAT1 signaling pathway." (PMID 25548224, 2015). "Taken together, our work suggests that oral administration of cimifugin ameliorates DSS-induced colitis and its associated lung inflammation, which is associated with its inhibition of chemokine release, reduction of M1 macrophage infiltration and down-regulation of JAK1/STAT1 protein expression." (PMID 40666519, 2025). "In the present study, phosphorylation of p65 and STAT1 was significantly reduced by the anti-colitis effects of PE-EPS in the DSS-induced colitis mice, and we speculated a prevention possibility of signaling crosstalk between STAT1 and NF-κB by PE-EPS treatment." (PMID 36080669, 2022). "Taken together, despite the well-described action of PTPN2 on multiple signaling cascades, loss of DC-specific PTPN2 resulted in increased levels of STAT1 phosphorylation in acute DSS-induced colitis but had no drastic changes in the overall inflammatory response." (PMID 34201918, 2021).
colitis (continued). "The impact of STAT1 signaling on gastrointestinal inflammation dependent on the localization of inflammation, as STAT1 is essential for intestinal epithelial cell death regulation in the small intestine, whereas it is not the key factor for intestinal epithelial cell death in the context of colitis." (PMID 34141714, 2021). "In the present study, we showed that QD exhibits a potent anticolitis effect in mice with experimental colitis by suppressing colonic oxidative stress and restraining colonic Th1/Th17 responses, which are associated with activating AMPK/Nrf-2 signals and inhibiting STAT1/STAT3 signals, respectively." (PMID 31737179, 2019). "Interestingly, this rescue was not complete as we also observed an increase in the SP of WT T cells upon NK cell depletion, which is consistent with the incomplete rescue of Stat1−/− T-cell expansion as well as the degree of colitis induced in Il10rb−/−Rag1−/− mice." (PMID 30796216, 2019). "However, the role of STAT1 in CRC is controversial and data for colitis‐associated CRC are limited." (PMID 29419930, 2018). "Specifically, ICI-colitis is enriched in mucosal Th1 effector cells that highly express IFNγ inducible genes such as STAT1, CD74, and GBP1/5 when compared to healthy controls and colitis-naïve patients." (PMID 39247203, 2024). "The administration of Gln via the rectal route in a rat colitis model downregulated the expression of regulatory inflammatory transcription factors (STAT1 and STAT5) and inflammatory factors, which alleviated the inflammatory effects of colitis." (PMID 36211442, 2022). "In contrast, Indigo Naturalis can inhibit STAT1/STAT3 signaling and protect against DSS-induced colitis in mice." (PMID 35873579, 2022). "It reduced TNBS-induced colitis and suppressed IFN-γ-induced STAT1 activation in colon cancer-derived CW-2 cells and T cell leukemia-derived Jurkat cells." (PMID 34068714, 2021). "During dextran sodium sulfate- (DSS-) induced colon inflammation and IFN-γ-treated macrophages, STAT1/IRF9 complex played a proinflammatory effect by regulating the transcription of CXCL10 gene." (PMID 34249133, 2021). "We have previously shown that STAT1 expression and phosphorylation levels are upregulated during DSS-colitis." (PMID 30538296, 2019). "As STAT1 is a critical regulator of Th1/Th17 differentiation, we further investigated its role in the ability of CD4+ T cells to induce colitis." (PMID 30796216, 2019). "Previous data show that IFNγ-mediated STAT1 signalling is a key requirement for intestinal caspase-11 upregulation and activation in IECs during DSS-colitis." (PMID 30538296, 2019). "Supporting the concept that spermidine protects from DSS colitis, it has been reported that this polyamine exhibits anti-inflammatory properties by dampening MAPKs, PI3K, STAT-1, and NF-κB signaling pathways in myeloid cells and thus gene transcription." (PMID 29922289, 2018). "Next, we analyzed Akt, STAT1 and STAT3 in colonic cell lysates of WT and Myo1F−/− animals that were induced to colitis." (PMID 30687322, 2018). "This increased STAT1 phosphorylation was recapitulated in vivo, i.e. in mesenteric lymph node T cells from mice with DSS-induced colitis or AOM-DSS-induced CAC." (PMID 27935860, 2017). "Taken together, miR-146a−/− mice appear to be protected from DSS colitis through a mechanism involving enhanced TLR/MyD88 and IFN/Stat1 signaling." (PMID 26456940, 2015). "Similar to caspase-11, STAT1 expression and phosphorylation levels were enhanced in the colon during DSS colitis." (PMID 25548224, 2015). "Consequently, genetic inhibition of STAT1 or the use of the JAK/STAT inhibitor upadacitinib (UPA) reversed the apoptotic phenotype of Rbbp9-/- organoids and mitigated the enhanced colitis observed in dextran sodium sulfate (DSS)-treated Rbbp9-/- mice." (PMID 39631567, 2025).
colitis (continued). "have documented that EZH2 deficiency suppressed M1 polarization and attenuated the inflammatory responses through the SOCS3/STAT1 pathway, leading to the suppression of autoimmune inflammation diseases including DSS-induced colitis in an experimental autoimmune encephalomyelitis (EAE) model." (PMID 35432300, 2022). "It has been reported Panax ginseng polysaccharides (GPS) relieved the DAI, colon length shortening, and pathological changes in colonic tissue in mice with colitis, while adjusting oxidative level and inflammatory cytokines through inhibiting the JAK2/STAT1/NLRP3 pathway." (PMID 35327312, 2022). "Our results demonstrate that STAT1 coordinates cell death in the ileum but not during experimental colitis." (PMID 34141714, 2021). "The reduction in the capacity of the IL-6ST/gp130 receptor to activate STAT1 and STAT3 in our heterozygous GP130∆STAT/+ mice demonstrates that IL-6ST/gp130 receptor signalling is required for the maintenance of intestinal barrier function during colitis." (PMID 33673239, 2021). "Surprisingly, in sharp contrast to our in vitro observation and in vivo data derived from the small intestine, STAT1 was not essential to orchestrate necrotic cell death during chemically induced colitis." (PMID 34141714, 2021). "In agreement with this is the fact that inflammation was reduced in Stat1−/− mice following DSS treatment, and an Ido1−/− mouse (Ido1 is up-regulated in S839I mice) shows a reduced severity to DSS-induced colitis." (PMID 34546338, 2021). "We next asked if Stat1−/− T cells were able to induce colitis in the absence of NK cells by transferring them into NK cell-depleted Il10rb−/−Rag1−/− mice." (PMID 30796216, 2019). "We next asked if the reduction of Stat1−/− T cells was dependent on colonic inflammation by transferring unfractionated WT or Stat1−/− CD4+ T cells into Rag1−/− mice, a strain that does not develop colitis when reconstituted with unfractionated WT T cells." (PMID 30796216, 2019). "In DSS-induced colitis mice, KA relieved the symptoms of colitis by suppressing inflammatory cell infiltration, restoring tight junction (TJ)- and epithelial–mesenchymal transition (EMT)-related protein expression, and inactivating AP-1, NF-κB, and STAT1/3." (PMID 31569788, 2019). "In the intestinal epithelium, deficiencies in STAT1, STAT3, or STAT5A did not lead to spontaneous inflammation, even though these mice were prone to chemical‐induced colitis." (PMID 29941542, 2018). "DSS‐induced colitis was reduced in STAT1 knockout mice whereas mice with haploinsufficiency of SOCS1, a negative regulator of STAT1, showed more severe colitis." (PMID 29419930, 2018). "We had demonstrated in vitro that LBP regulated M1/M2 macrophage polarization by modulating the STAT1 and STAT6 pathways, and also found that LBP could regulate macrophage polarization in DSS-induced colitis mice by the detection of the expression of M1 or M2 marker in colon tissue." (PMID 37144216, 2023). "However, contrasting with what we observed in vitro and in the thymus, peripheral Treg were virtually absent in STAT1 KO spleens, consistent with colitis and with an inability to suppress TH17 expansion." (PMID 34378531, 2021). "Collectively, these data suggested that the ITGB6 transgene dysregulated the secretion of pro‐inflammatory cytokines, upregulated the expression of integrin ligands and the phosphorylation of Stat1 in DSS‐induced colitis in mice, which might contribute to DSS‐induced colitis." (PMID 33491282, 2021). "Thus, the absence of STAT1 results in impaired macrophage recruitment during colitis cancer progression." (PMID 34299314, 2021). "Given that knockdown of Stat3 does not have an effect on Stat1 expression in shStat3 mice and the similar disease phenotype in GP130∆STAT/+ and shStat3 mice after DSS treatment, these further support that STAT3, but not STAT1, confers protection against colitis." (PMID 33673239, 2021).
colitis (continued). "Here the authors show that Stat1 also serves to protect CD4 T cells from natural killer cell-mediated killing, potentially by promoting the expression of Nlrc5 and MHC-I, to preserve the induction of experimental colitis via the adoptive transfer of CD4 T cells." (PMID 30796216, 2019). "Ifnar1−/−Ifngr1−/− T cells were also able to induce colitis unlike Stat1−/− T cells." (PMID 30796216, 2019). "This is in agreement with other studies that found that male mice respond faster and develop a more significant and aggressive colitis relative to female mice when exposed to DSS, and that STAT-1 deficiency or IRAK-1 deficiency render male, but not female, mice more resistant to DSS-induced colitis." (PMID 30619283, 2018). "We found that p-STAT1 binds to EP300 to regulate the expression of LCP2 and TNFAIP2 by promoting H3K27 acetylation at enhancers, and thus, we further investigated whether the increase in H3K27ac levels mediated by EP300 is involved in the development of colitis in mice." (PMID 34112215, 2021).